RPL31 (ribosomal protein L31)
Description:
Component of the large ribosomal subunit. The ribosome is a large ribonucleoprotein complex responsible for the synthesis of proteins in the cell.
Synonyms: L31; eL31
Tractability: Small molecule: an approved drug acts on it; a structure with a bound ligand is known; a high-quality ligand is known. PROTAC: ubiquitination databases record sites on it; its protein half-life has been measured; a small molecule that binds it is known. Other modalities: a drug acting on it is in phase 2 or 3 trials.
Target class: Other cytosolic protein
Gene: Protein-coding gene on chromosome 2 (101,002,229 to 101,024,032, forward strand). Ensembl gene ENSG00000071082.
Subcellular location: Cytoplasm
Pathways (Reactome):
Metabolism of proteins: Eukaryotic Translation Termination; Formation of a pool of free 40S subunits; GTP hydrolysis and joining of the 60S ribosomal subunit; L13a-mediated translational silencing of Ceruloplasmin expression; PELO:HBS1L and ABCE1 dissociate a ribosome on a non-stop mRNA; Peptide chain elongation; Ribosome Quality Control (RQC) complex extracts and degrades nascent peptide; SRP-dependent cotranslational protein targeting to membrane; ZNF598 and the Ribosome-associated Quality Trigger (RQT) complex dissociate a ribosome stalled on a no-go mRNA
Metabolism of RNA: Major pathway of rRNA processing in the nucleolus and cytosol; Nonsense Mediated Decay (NMD) enhanced by the Exon Junction Complex (EJC); Nonsense Mediated Decay (NMD) independent of the Exon Junction Complex (EJC)
Cellular responses to stimuli: Response of EIF2AK4 (GCN2) to amino acid deficiency
Developmental Biology: Regulation of expression of SLITs and ROBOs
Disease: Viral mRNA Translation
Metabolism: Selenocysteine synthesis
Gene Ontology:
Molecular function: protein binding; RNA binding; structural constituent of ribosome
Biological process: cytoplasmic translation; negative regulation of myoblast fusion; spermatogenesis; striated muscle contraction; translation
Cellular component: cytoplasm; cytosolic large ribosomal subunit; cytosolic ribosome; extracellular exosome; focal adhesion; membrane; cytosol; large ribosomal subunit; nucleoplasm; ribosome; synapse
Genetic constraint (gnomAD): Loss-of-function variants: 0 observed, 13.79 expected, observed/expected ratio (o/e) 0, 90% interval 0 to 0.22. The upper end of that interval is the gene's LOEUF score, 0.22, which puts it in group 1 of 6, group 1 being the genes least tolerant of losing a copy. Missense variants: 92 observed, 164.97 expected, observed/expected ratio (o/e) 0.56, 90% interval 0.47 to 0.66. Synonymous variants: 49 observed, 54.29 expected, observed/expected ratio (o/e) 0.9, 90% interval 0.72 to 1.14.
Homologues: Orthologues: rat Rpl31 (100% identical), zebrafish rpl31 (92% identical), tropical clawed frog rpl31 (89% identical), Drosophila melanogaster RpL31 (67% identical), Caenorhabditis elegans rpl-31 (66% identical).
Diseases named in the same sentence as RPL31 in open-access papers:
RPL31 is named in the same sentence as 38 diseases in open-access papers, as found by Europe PMC text mining. Sharing a sentence is not in itself a finding about the gene and the disease. The quoted sentences say what the papers report.
prostate carcinoma (6 papers, 2014 to 2022). A carcinoma that arises from epithelial cells of the prostate gland. "Thus, polymorphisms of NPAS2-RPL31 regions are involved in a linkage disequilibrium block based on the HapMap Project data and could also affect prostate cancer risk by putatively modulating RPL31 expression." (PMID 25285958, 2014). "We focused on the characterization of ribosomal protein RPL31 in prostate cancer biology, as silencing of RPL31 substantially reduced cell cycle progression of BicR cells." (PMID 25285958, 2014). "In an RNA-sequencing study integrated in The Cancer Genome Atlas, RPL31 expression was also elevated in prostate cancers compared with normal prostate tissues." (PMID 25285958, 2014). "Taken together, these results suggest that RPL31 positively contributes to the development and phenotype of prostate cancer." (PMID 25285958, 2014). "In a comparison of prostate carcinoma specimens and normal prostate samples at a threshold of at least a 2-fold change (P<0.01), RPL31 upregulation was observed in the study conducted by Tomlins and colleagues." (PMID 25285958, 2014). "We found that the expression level of RPL31 mRNA was significantly elevated in BicR cells compared with LNCaP cells, and clinical studies show that RPL31 expression in prostate carcinoma is higher than that in benign prostate tissues." (PMID 25285958, 2014). "Of note, RPL31 was also upregulated in clinical studies examining prostate cancer by microarray or RNA sequencing, indicating its tumor-promoting contribution in this disease as well." (PMID 25285958, 2014). "We sought to determine the mechanism by which RPL31 knockdown severely growth arrested BicR prostate cancer cells." (PMID 25285958, 2014). "Of note, RPL31 mRNA is more abundantly expressed in BicR cells than in parental LNCaP cells, and clinical data from ONCOMINE and The Cancer Genome Altas showed that RPL31 is overexpressed in prostate carcinomas compared with benign prostate tissues." (PMID 25285958, 2014). "RPL31 could be used as the molecular treatment target for advanced prostate cancer, and we presume that RPL31 could also be used as a target for ovarian cancer treatment." (PMID 33278864, 2021). "Because bicalutamide treatment in prostate cancer cells impairs ribosomal RNA synthesis, RPL31 knockdown could further aggravate the dysregulation of ribosomal function in the presence of bicalutamide." (PMID 25285958, 2014). "Therefore, we further investigated the pathophysiological role of RPL31 in prostate cancer cells." (PMID 25285958, 2014). "To explore whether RPL31, HIST1H2BD, and ADAMTS1 expression levels were altered in clinical prostate cancer samples, we assessed the expression status of these genes based on the ONCOMINE microarray dataset." (PMID 25285958, 2014).
breast carcinoma (5 papers, 2017 to 2024). "RPL31 is implicated in modulating the tumor immune microenvironment and has been recognized as a protective factor in breast cancer pathology." (PMID 38404591, 2024). "To explore it, we analyzed the differentially expressed genes of RPL31+ subset compared with FOSB+ subset in breast cancer as well as mast cells in normal breast tissues, respectively." (PMID 39104420, 2024). "In the TCGA dataset, C11orf1, OLA1, RPL31, SPDL1 and IL33 were identified to be associated with prognosis of breast cancer." (PMID 35761863, 2022). "Collectively, our results suggested that RPL31+ mast cells might be an indicator of better prognosis in ER+ breast cancer patients." (PMID 39104420, 2024). "The mast cells in breast cancer were divided into FOSB+ and RPL31+ subsets." (PMID 39104420, 2024). "Strikingly, ER+ and TNBC subtypes exhibited significantly higher RPL31+ subset than FOSB+ subset, whereas the HER2+ subtype exhibited a higher FOSB+ subset than RPL31+ subset, indicating that the imbalance of these two subsets might influence the prognosis of breast cancer patients." (PMID 39104420, 2024).
atherosclerosis (2 papers, 2021 to 2025). A disease characterized by the build-up of fatty material and calcium deposition in the arterial wall resulting in partial or complete occlusion of the arterial lumen. "Early studies have reported that RPL31 is suppressed in proliferative VSMCs, while the deficiency of RPL31 in macrophages would accelerate atherosclerosis by suppressing the synthesis of a series inflammatory proteins." (PMID 33510838, 2021).
COVID-19 (2 papers, 2021 to 2023). A disease caused by infection with severe acute respiratory syndrome coronavirus 2. "The key genes were involved in 23 KEGG pathways, including COVID-19 (involving RPL9 and RPL31), hepatitis C, influenza A, and ribosome (involving RPL9 and RPL31)." (PMID 35047519, 2021).
rheumatoid arthritis (2 papers, 2022 to 2024). A chronic, systemic autoimmune disorder characterized by inflammation in the synovial membranes and articular surfaces. "Researchers implicate autoantigens, including RPL7, RPL31, RPL14, and RPL9, in the regulation of diseases such as systemic lupus erythematosus, rheumatoid arthritis, and systemic sclerosis." (PMID 35432523, 2022). "Although RPL31 was reported to be important in regulation of osteogenic differentiation, and was identified as one of the top dysregulated genes in the synovium of rheumatoid arthritis (RA) patients, the exact role of RPL31 in synovial aging or diseases remains unexplored." (PMID 38092362, 2024).
Alzheimer disease (1 paper, 2024). A progressive, neurodegenerative disease characterized by loss of function and death of nerve cells in several areas of the brain leading to loss of cognitive function such as memory and language. "Notably, six of these proteins (RPS3A, RPS4X, RPS8, RPS14, RPS20 and RPL31) were upregulated in brain capillaries of Alzheimer’s disease patients." (PMID 38732249, 2024).
colon cancer (1 paper, 2024). "RPL31 is involved in cell proliferation and has been found to be overexpressed in colon cancer." (PMID 39165691, 2024).
colorectal adenocarcinoma (1 paper, 2025). The most common type of colorectal carcinoma. "It was found that elevated expression of RPL31, CCT2, RPL17, and NUP85, as well as downregulation of NUP98, CDC37, DNM2, and SNRPN resulted from corresponding μ-ASOs treatment, correlating with improved survival in colorectal adenocarcinoma patients according to the TCGA database." (PMID 41373892, 2025).
colorectal tumors (1 paper, 2014). "Regarding the pathological role of RPL31 in human tumors, it has been reported that RPL31 mRNA is upregulated in colorectal tumors." (PMID 25285958, 2014).
depression (1 paper, 2025). "Additionally, diminished expression of a transcript variant of the RPL31P12, which encodes for the ribosomal protein L31 pseudogene 12, was linked to major depressive disorder, suggesting a shared genetic pathway influencing both depression and obesity risk." (PMID 40405979, 2025).
diabetes (1 paper, 2016). "We have identified some potential lncRNAs, such as Rpl31-ps7, AB352974, Rpl35a-ps7, Rn4.5s, and XLOC_01985, associated with diabetes-related phenotypes." (PMID 27119337, 2016).
influenza (1 paper, 2023). An acute viral infection of the respiratory tract, occurring in isolated cases, in epidemics, or in pandemics; it is caused by serologically different strains of viruses (influenzaviruses) designated A, B, and C, has a 3-day incubation period, and usually lasts for 3 to 10 days. "In a separate pediatric study, EEF1G mRNA expression and specifically RPL31, were reported to be decreased in PBMCs from influenza-infected children following hospitalization and could be used to distinguish between influenza and bacterial infections (with and without lung involvement)." (PMID 37533854, 2023).
malignant lymphoma (1 paper, 2021). "RPS21, MRPS28, RPL31, and RPL30 showed relatively higher protein expressions in some DLBCL and other malignant lymphoma tissues than the averaged expressions in normal tissues, though not significant." (PMID 34760386, 2021).
nasopharyngeal carcinoma (1 paper, 2014). A carcinoma arising from the nasopharyngeal epithelium. "In a screening of tumor antigen genes from a cDNA library, RPL31 was identified as one of 6 genes in nasopharyngeal carcinoma." (PMID 25285958, 2014).
osteoporosis (1 paper, 2017). A condition of reduced bone mass, with decreased cortical thickness and a decrease in the number and size of the trabeculae of cancellous bone (but normal chemical composition), resulting in increased fracture incidence. "All of the functional evidence suggested the important functional mechanisms underlying the associations of the 2 SNPs (rs2278729 and rs3736228) and 3 genes (RPL31, CPT1A and MTL5) with osteoporosis." (PMID 28369098, 2017).
renal cell cancer (1 paper, 2020). "In a previous study, high expression of RPL31 was closely associated with poor prognosis in renal cell cancer (The Human Genome Atlas), suggesting inversely low expression of RPL31 may be correlated with good prognosis of ccRCC." (PMID 32039517, 2020).
systemic vasculitis (1 paper, 2023). "Ribosomal-related genes such as RPL31 and RPL9 may be implicated in the pathogenesis of systemic vasculitis, which is thought to be uncontrolled genetics that promotes Takayasu arteritis through controlling ribosome pathways." (PMID 38275601, 2023).
tumor (13 papers, 2014 to 2024). "This decrease in tumor burden corresponded with a >25% reduction in RPL31 staining of tumor sections, further substantiating a role for UBAP2L in regulating translation in vivo in PDAC." (PMID 37673892, 2023). "Although a gain-of-function study of RPL31 isolated from the giant panda showed its anticancer function in human cancer cells, clinical studies reveal a tumor-promoting role for RPL31 in human malignant tissues." (PMID 25285958, 2014). "Furthermore, these immune cells in TME underwent transcriptional reprogramming, including CD8 + T subgroups of CCR7 + and IL7R+, as well as M2-like monocyte subgroups expressing tumor-associated signature genes, like CCR7, SGKI, and RPL31." (PMID 37221625, 2023). "RPL30, RPL31, RPS25, and FAU positively correlated with tumor-infiltrating lymphocytes (TIL) and macrophages." (PMID 34760386, 2021). "Moreover, we identified four putative tumor-specific cryptic peptides from ZYG11A, RPL36A-HNRNPH2, CLIC1 and RPL31 that were decreasingly presented upon MAPKi in SK-Mel-28 wt but were unaffected in SK-Mel-28 dr cells, indicating a direct link to MAPK signaling." (PMID 39835134, 2024).
cancer (10 papers, 2014 to 2024). A tumor composed of atypical neoplastic, often pleomorphic cells that invade other tissues. "Among nine candidate oncogenes, high expression of four genes including RFTN1, HMGB1, RPL24, and RPL31 were reported to be correlated with a poorer prognosis in cancers (conversely, one may say that low expression of such genes shows good prognosis)." (PMID 32039517, 2020). "Although this finding is not direct evidence for an association of RPL31 expression with cancer prognosis, low expression of RPL31 may influence patients’ prognosis in cancer." (PMID 32039517, 2020). "In addition, siRNA-mediated silencing of all transcripts of eight genes that showed a consistent differential splicing signature across multiple cancer types (ABCC5, ANKHD1, DYNLL1, F8, RPL31, TMEM14C, UQCC, and CRNDE) failed to reveal differences in cell viability." (PMID 25424858, 2015).
infection (2 papers, 2014 to 2021). The state of being infected such as from the introduction of a foreign agent such as serum, vaccine, antigenic substance or organism. "Interestingly, RPL31 and IL8 were almost exclusively expressed after Lena infection, while other genes, including CCL2 and ACADVL, were differentially regulated by infection with both strains, although to different extents." (PMID 24643046, 2014).
RPL31 also shares sentences with these, for which no sentence is quoted: colorectal cancer (2 papers); pancreatic cancer (2); bacterial infections (1); brain disease (1); Diamond-Blackfan anemia (1); glioma (1); hepatitis C (1); invasive breast carcinoma (1); melanoma (1); Obesity (1); ovarian carcinoma (1); papillary carcinomas of the breast (1); Sepsis (1); Stroke (1); systemic lupus erythematosus (1); systemic sclerosis (1); Takayasu arteritis (1); uveal melanoma (1).